RUNDC3A-AS1 (RUNDC3A antisense RNA 1)
Gene: Long non-coding RNA gene on chromosome 17 (44,299,567 to 44,315,515, reverse strand). Ensembl gene ENSG00000267750.
Gene Ontology:
Biological process: RNA processing
Cellular component: nucleolus